KRAS (KRas proto-oncogene, GTPase)
Diseases named in the same sentence as KRAS in open-access papers (continued):
Sharing a sentence is not in itself a finding about the gene and the disease.
lung cancer (continued). "A substantial number of studies related to the biology of KRAS have been performed and are being published almost every day, notably into lung cancer, highlighting the fact that this topic represents a huge stake in thoracic oncology." (PMID 35406400, 2022). "We were ultimately successful ingenerating a transplantable KRAS mutant lung cancer model that is partiallysensitive to immunotherapy and shows a response to KRAS targeted agents that ispotentiated by adaptive immunity." (PMID 35930804, 2022). "KRAS has long been known to be a driver in lung cancer and CRC as well as a well-established acquired resistance mechanism to targeted therapies in lung, CRC, and other rare cancer types." (PMID 35862868, 2022). "In the following, we discuss pivotal findings concerning KRAS-driven cytokine and chemokine networks in lung cancer." (PMID 36074553, 2022). "Together, these results unravel a signaling cascade from the IRE1α-mediated UPR to p38 MAPK and to mTOR signaling in KRAS-mutant lung cancer upon NOP56 suppression." (PMID 35039048, 2022). "Combination treatment with MA and osimertinib improved the sensitivity of lung cancer cells to EGFR-TKIs through ROS suppression of the KRAS-ERK signaling pathway, as well as NRF2-SLC7A11 axis inhibition- and mitochondrial Ca2+ overload-triggered ferroptosis." (PMID 36712673, 2022). "In fact, the Qo site of the mitochondrial complex III has been identified as the main site of KRAS-driven ROS generation in a mouse model of lung cancer." (PMID 35359456, 2022). "BCL6 inhibition significantly triggered stalled replication forks and growth arrest, thereby blocking the malignant phenotype of KRAS-mutant lung cancer cells." (PMID 36377663, 2022). "In our study, we found that lung cancer cell line H460, which harbors a KRAS Q61H mutation, was maximally sensitive to TIR-199 within the lung cancer panel." (PMID 35088066, 2022). "LKB1 is frequently concomitant with KRAS in lung cancers and KRAS oncogenic mutants upregulate glycolysis." (PMID 35573694, 2022). "This work provides insight towards better understanding trametinib resistance and improving the clinical utilization of MEK inhibitors for the treatment of patients with KRAS mutant lung cancer." (PMID 36418460, 2022). "Our in vivo studies showed that inhibition of BCL6 transcriptional activity by COMP7 significantly impeded the growth of KRAS-mutant lung cancer cells in preclinical mouse models." (PMID 36377663, 2022). "First of all, KRAS and EGFR mutations have profound effects on the treatment and prognosis of lung cancer patients." (PMID 35392225, 2022). "FOSL1 is a transcription factor, and high expression of FOSL1 predicts poor prognosis in mutant KRAS lung cancer." (PMID 36712848, 2022). "The glutaminase inhibitor CB-839 has been shown to produce an anti-tumor effect in KRAS-mutant lung cancer cells which carry inactivation of the KEAP1 gene resulting in NRF2 hyperactivation and xCT overexpression." (PMID 36338517, 2022). "Synergism between MEK and FGFR inhibition has previously been established in the context of KRAS mutant lung cancer: a shRNA screen of Tra-treated H23 KRASG12C lung cancer cells identified FGFR1 signaling as compensatory for MEK inhibition." (PMID 35739276, 2022). "Nevertheless, KRAS-mutant lung cancers respond differently to immunotherapy and show differences in terms of the immunogenic profile." (PMID 36012655, 2022). "In mouse models, a combination of carboplatin chemotherapy and sotorasib in KRAS G12C lung cancer resulted in greater tumor regression than either monotherapy." (PMID 36230484, 2022).
lung cancer (continued). "KRAS mutational status was analyzed using next‐generation sequencing of 150,327 NSCLC patients from the Lung Cancer Big Data Precise Treatment Collaboration Group (LANDSCAPE) project (Cohort I)." (PMID 35394121, 2022). "KRAS is the most common alteration identified in solid tumors and especially in pancreatic (88%), colorectal (45–50%) and lung cancers (31–35%)." (PMID 36012655, 2022). "Moreover, GEO data regarding gene-edited mouse models revealed that the expression of hub genes increased with the progression of NSCLC, and cohort study in lung cancer showed that the hub genes may be involved in EGFR- or KRAS-mutation driven NSCLC progression." (PMID 36176446, 2022). "Overexpression of ILK in lung cancer cells results in the upregulation of PINCH1, β-parvin, and Ras suppressor protein 1 (RSU1) expression, while pharmacologic inhibition of ILK in KRAS-mutant lung cancer cells suppressed cell growth, migration, and EMT." (PMID 35804980, 2022). "It was also previously reported that the inhibition of MAPK and CDK4/6 induces cell cycle arrest and senescence in KRAS-mutant lung cancer cells." (PMID 35614034, 2022). "We therefore investigated the effects of KRASG12C inhibition in a new immunogenic model of KRAS-mutant lung cancer." (PMID 35857848, 2022). "While studied mainly in other KRAS dependent cancers, the importance of the RAL/TBK1 pathway in RAS-induced lung cancer was confirmed in an RNAi screen to identify lethal partners of oncogenic KRAS." (PMID 35406400, 2022). "Analysis of human lung cancer data sets derived from The Cancer Genome Atlas (TCGA) showed that KRAS, RAF1, MAP2K1, MAP2K2, MAPK3, and MAPK1 expression levels were positively correlated with the BCL6 expression level." (PMID 36377663, 2022). "And recently, RGS3 was reported to hinder the effect of KRASG12C inhibitors in the targeted therapy of lung cancer by enhancing the GTPase activity of KRAS." (PMID 36214767, 2022). "This is particularly urgent in lung cancer, where mutations in EGFR, ALK, ROS, RET, METex14 skipping, BRAF, and KRAS should be identified before initial treatment." (PMID 35862868, 2022). "Murine models of KRAS-driven lung cancer suggest that IL-17A and IL-17A-expressing lymphocytes mediate tumor-associated inflammation and tumor cell proliferation." (PMID 35883573, 2022). "KRAS belongs to the canonical RAS family of genes and mutation in KRAS is a common oncogenic event in lung cancer." (PMID 36359882, 2022). "When combined with BI-2536 (an inhibitor of polo-like kinase 1), Fasudil suppressed KRAS-mutant lung cancer growth in a corresponding LSL-KRAS (G12D) mouse model and in a patient tumor explant mouse model of KRAS-mutant lung cancer." (PMID 36230634, 2022). "KRAS amplification contributes to the resistance to MET inhibition in lung cancer, and MET amplification was noticed in the acquired resistance to the KRAS G12C inhibitor." (PMID 36230855, 2022). "Our in vitro and in vivo pharmacological studies collectively demonstrate that BCL6 serves as a potential therapeutic target for the treatment of KRAS-mutant lung cancer." (PMID 36377663, 2022). "Here, we investigated acquired resistance to MEK inhibition by generating isogenic pairs of trametinib-sensitive and -resistant KRAS mutant lung cancer cell lines through trametinib dose escalation studies." (PMID 36418460, 2022).
lung cancer (continued). "BCL6 maintained the global expression of prereplication complex components; therefore, BCL6 inhibition induced stalling of the replication fork, leading to DNA damage and growth arrest in KRAS-mutant lung cancer cells." (PMID 36377663, 2022). "Although KRAS(G12C) and immune checkpoint inhibitors have been approved for the treatment of lung cancer, other KRAS-mutant subtypes lack effective targeted therapies." (PMID 36377663, 2022). "Together, these results support a model that NOP56 downregulation induces a metabolic vulnerability to mTOR inhibition, which presents a new and rational strategy for treating KRAS-mutant lung cancer." (PMID 35039048, 2022). "It has also been reported that lupeol, a substance abundant in vegetables, suppresses STAT3 activation, which is upregulated in KRAS mutant lung cancer." (PMID 36348317, 2022). "The results of our transactivation assays show that TGFβ1 exposure up-regulates the transcriptional activity of ACSL3. mTORC1 signaling pathway has been reported to mediate the up-regulation of ACSL3 expression in mutant KRAS lung cancer cells." (PMID 35414781, 2022). "Overexpression of UHRF1 rescued double-strand break repair, and depletion of UHRF1 reduced the chemosensitivity of KRAS mutant lung cancer cells." (PMID 35884544, 2022). "KIMAT1 has been identified as a KRAS-responsive lncRNA whose expression is correlated with expression level of KRAS in lung cancer cell lines as well as clinical samples." (PMID 35139853, 2022). "From October 2017 to September 2020, KRAS-mutant lung cancer was detected, using NGS, in 1132 patients in Shanghai Chest Hospital, Shanghai Jiaotong University." (PMID 35887766, 2022). "As reported in our recent work, BCL6 activation attenuated the antitumor efficacy of clinical BET inhibitors in KRAS-mutant lung cancer." (PMID 35503721, 2022). "Single targeting of MEK was insufficient to inhibit KRAS-driven lung cancer, partly because of sustained ERK reactivation." (PMID 36377663, 2022). "The results showed that the lung cancer cell line HCC2429, in which KRAS mutated at position 12V had been transfected, showing a decrease in the apoptotic response after radiation." (PMID 35565331, 2022). "One previously explored avenue for the treatment of KRAS-driven lung cancers is through the inhibition of downstream pathway effectors." (PMID 36418460, 2022). "We recently revealed that BCL6 enables solid tumor cells to evade genotoxic stress, and pharmacological inhibition of BCL6 enhances the sensitivity of KRAS-mutant lung cancer cells to clinical BETi." (PMID 36377663, 2022). "The occurrence of KRAS mutations differs based on the specific lung cancer type/subtype, being higher in NSCLC than in SCLC, and within NSCLC, KRAS mutations are more frequent in lung AC than SCC." (PMID 36077640, 2022). "Little is known about the ICI efficacy among Asian patients with lung cancer harboring KRAS alterations owing to the lower prevalence of these alterations compared to that in western populations." (PMID 35491960, 2022). "Third, Wt patients are a heterogeneous population that includes patients with KRAS, ALK, and ROS-1 mutation lung cancer." (PMID 36085020, 2022). "Our analysis has gained insight into the different mechanisms by which oncogenic KRAS signaling mediates immune evasion in lung cancer." (PMID 35857848, 2022). "While the KRASG12C mutation is only found in 3 to 4% of colon carcinoma, it is more prevalent in NSCLC (~14%) and clinical efficacy of the KRAS inhibitors also seems to be higher in lung cancer." (PMID 35857848, 2022). "Other evidences show that inhibition of SOD1 by ATN-224 induces cell death in various non–small-cell lung cancer (NSCLC) cells, including those harboring KRAS mutations." (PMID 35978820, 2022).
lung cancer (continued). "Evaluation of KZNF expression in TCGA LUAD RNA-seq data revealed their significant downregulation in mutant KRAS(G12D) samples when compared to WT KRAS lung cancer or matched normal samples, respectively." (PMID 35858545, 2022). "MKRN3 is frequently mutated in non–small-cell lung cancers (NSCLCs), and genomic aberrations of MKRN3 are found to be enriched in NSCLC samples harboring KRAS mutations." (PMID 35281811, 2022). "Our recent work additionally revealed that an increased expression of BCL6 largely contributes to the resistance of KRAS-mutant lung cancer to clinical BET inhibitors." (PMID 35503721, 2022). "KRAS G12C inhibitors such as sotorasib and adagrasib are often effective in KRAS G12C–driven non–small cell lung cancer (NSCLC) patients." (PMID 35166243, 2022). "A similar result was seen in a KRAS-mutant lung cancer cell line, wherein, the authors were able to classify KRAS-mutant cancer cells as KRAS-dependent or KRAS-independent." (PMID 36284306, 2022). "Analysis of IMPOWER 150 also presented that, for the subgroup of patients with KRAS-mutant lung cancer carrying STK11 and/or Keap1 simultaneously, Atezolizumab combined with Bevacizumab and chemotherapy is an effective first-line treatment." (PMID 35887766, 2022). "EGFR palmitoylation has been shown to inhibit EGFR activity and alter downstream signaling in the KRAS mutant lung cancer." (PMID 36619616, 2022). "Kirsten rat sarcoma viral oncogene homolog (KRAS) is an important driver gene of non‐small cell lung cancer (NSCLC)." (PMID 35394121, 2022). "KRAS mutations are mutually exclusive with alterations in other molecular markers such as EGFR, ALK and ROS1, considered genetic drivers of lung cancer development." (PMID 36077640, 2022). "ACSL3 silencing induced cell death in vitro by depleting cellular ATP and impaired tumor growth in vivo, suggesting the involvement of this enzyme in mutant KRAS lung cancer growth." (PMID 35159223, 2022). "To understand the functional relationship between DX2 and KRAS, we altered DX2 levels by ectopic expression of Strep-DX2 and si-DX2 in H460 lung cancer cells, and checked the change in KRAS levels." (PMID 35546148, 2022). "In KRAS-driven lung cancer or cholangiocarcinoma models, the knock-out of Fra1 significantly delays tumor development." (PMID 36534167, 2022). "ALK mutations are mutually exclusive with EGFR and KRAS mutations in many patients, positioning ALK as the primary target for treatment in ALK-positive lung cancers." (PMID 36230484, 2022). "Circ_GLG1/miR-622, circFNTA/miR-370-3p and circ-MEMO1/miR-101-3p axes have been shown to regulate expression of KRAS in colorectal, bladder and lung cancer cells." (PMID 35139853, 2022). "CtDNA from 458 primary lung cancer patients was analyzed using a panel of multiplex ddPCRs for EGFR (Ex19Del, G719S, L858R, L861Q and S768I), KRAS G12/G13 and BRAF V600 mutations." (PMID 36413862, 2022). "In our study, we identified BCL6, a master regulator of germinal-center response, as a promoting factor for KRAS-mutant lung cancer." (PMID 36377663, 2022). "In KRAS-driven lung cancer, targeting of RAF1 was suggested to be a tumor-selective strategy since RAF1 was found to be essential for tumor initiation." (PMID 35965494, 2022). "Using transgenic mouse model of lung cancer, we showed that Zno/K* lung cancers were sensitive to combinational therapy with NF-κB inhibitor, KRAS inhibitor and PD-1 antibody." (PMID 36457047, 2022). "It is known that oncogenic KRAS stimulates transformation and lung cancer cell proliferation, at least in part, by induction of NRF2." (PMID 35052618, 2022). "To test this possibility, we knocked down NOP56 in KRAS-mutant lung cancer cells (H358, H460) by using short-hairpin RNAs (shRNA)." (PMID 35039048, 2022).
lung cancer (continued). "Their inhibition in a KRAS-mutant human lung cancer cell line resulted in improved responses with MEK inhibitors." (PMID 34728792, 2022). "RUNX3, which serves as a mediator of multiple tumor suppressor pathways, is inactivated in KRAS mutant lung cancer." (PMID 36619616, 2022). "It explored the differences in efficacy in respective first-line treatments by genotyping them through the analysis of genome profiles to excavate the efficacy predictors of KRAS-mutant lung cancer and the prognostic value of different genotypes." (PMID 35887766, 2022). "Geneticallyengineered mouse models (GEMMs) have been extensively used to gain mechanisticinsights into the biology of KRAS-mutant lung cancer and to assess the efficacy ofnovel therapeutics." (PMID 35930804, 2022). "Together, these results support that iRhom-dependent shedding of ERBB ligands in the extracellular medium drives a positive feedback loop to maintain the activity of oncogenic KRAS in lung cancer cells." (PMID 35971826, 2022). "Pharmacologic inhibition of ILK in KRAS-mutant lung cancer cells increases sensitivity to platinum-based chemotherapy." (PMID 35804980, 2022). "A vaccine using peptides computationally predicted to target neoantigens derived from mutant KRAS elicited an immune response in a mouse model of KRAS-driven lung cancer in which mice were vaccinated prior to activating the mutant KRAS gene." (PMID 36476325, 2022). "Tumors that escape KRAS suppression in a KRAS-driven murine lung cancer model show high YAP1 activity and upregulation of epithelial-to-mesenchymal transition (EMT)-like transcriptional programs." (PMID 35883668, 2022). "Based on a subgroup analysis, in the CheckMate 057 trial, patients with KRAS-mutant lung cancers achieved the greatest OS benefit when comparing immune checkpoint inhibitors (ICIs) with chemotherapy (HR 0.52, 95% CI: 0.29–0.95)." (PMID 36012655, 2022). "KRASG12C inhibitors will undoubtedly have a profound impact on the treatment of KRAS‐driven lung cancer." (PMID 34951114, 2022). "EZH2 was also highly expressed in the lung cancer with positive KRAS expression, exhibiting a positive correlation, as well as with the expression of BRAF, especially in lung squamous cell carcinoma." (PMID 36195655, 2022). "Our results showed that BCL6 inhibition exerted little effect on ROS production in KRAS-mutant lung cancer cells, thus excluding the role of ROS in BCL6-mediated tumor-promoting action in the context of KRAS mutational activation." (PMID 36377663, 2022). "Of note, only certain KRAS mutant lung cancers (those expressing both galectin-3 and integrin αvβ3) rely on a process of anchorage-independent growth, showing the close relationship between membrane signaling and KRAS dependence in lung cancer." (PMID 35406400, 2022). "To test this possibility, we analyzed the cell cycle progression in KRAS-mutant lung cancer cells after BCL6 depletion alone or in combination with BCL6 reconstitution." (PMID 36377663, 2022). "Inhibition of both MEK and CDK4/6 by palbociclib induced responses in mutant KRAS colorectal and lung cancer models." (PMID 36048281, 2022). "For the CAM tumor, we used the tumor formed by transplanting lung cancer cell line A549, as these cells carry the mutant KRAS gene." (PMID 35205697, 2022).